IGF1 (insulin like growth factor 1)
Diseases named in the same sentence as IGF1 in open-access papers (continued):
Sharing a sentence is not in itself a finding about the gene and the disease.
acne (108 papers, 2010 to 2025). An inflammatory process of the sebaceous glands which is characterized by comedones, nodules, papules and/or pustules on the skin. "The association between milk and acne has been attributed to the presence of a growth hormone, insulin‐like growth factor 1 (IGF‐1), which is believed to be more prevalent in milk with a reduced fat content." (PMID 40013532, 2025). "High glycaemic diets and milk consumption have been linked to increased acne severity, potentially due to IGF-1 activation." (PMID 40006023, 2025). "Increased blood glucose levels were linked to acne patients mostly because they cause insulin to be secreted, which reduces the binding protein for IGF-1 and encourages IGF-1 cell proliferation." (PMID 38255795, 2024). "Insulin-like growth factor-1 (IGF-1) is considered as a pathogenic factor contributing to sebaceous gland dysfunction, which leads to acne vulgaris." (PMID 39349732, 2024). "Higher insulin results in the higher production of hepatic insulin-like growth factors (IGF-1), which is linked with the increased production of sebum from the sebaceous glands, a major factor involved in the pathogenesis of acne." (PMID 39624570, 2024). "Dairy products have been thought to be associated with the worsening of acne and HS, likely due to influences on insulin-like growth factor 1 (IGF-1)." (PMID 39598237, 2024). "In fact, these foods cause an increase in IGF-1 production, with consequent cell proliferation in the skin, hyperproduction of sebum and the onset of acne." (PMID 38255133, 2024). "Previous studies had demonstrated that IGF-1 was elevated in acne patients, indicating that IGF-1 and downstream signaling pathways were associated with the severity of acne." (PMID 38197658, 2024). "A Western diet, especially the consumption of hyperglycemic carbohydrates, milk and yogurt, has been associated with IGF-1-mediated acne pathogenesis." (PMID 37998335, 2023). "Although the impact of androgens on the pathogenesis of acne is well accepted, recent observations underline a complex, synergistic crosstalk between IGF-1, insulin and androgens in the activation of AKT and mTORC1." (PMID 37998335, 2023). "IGF-1 levels also stimulate the production of androgens, which are associated with sebum production and thus the development of acne." (PMID 36986218, 2023). "More frequent dairy intake in acne patients was associated with elevated IGF-1 levels compared to patients with normal IGF-1 levels." (PMID 37892480, 2023). "Classically, acne has been associated with an increase in androgens at the systemic and local levels, but the influence of IGF-1 and insulin, which in turn are dependent on diet, is transcendental." (PMID 35889022, 2022). "A growing body of evidence underlines the role of increased insulin-like growth factor-1 (IGF-1) signaling in the pathogenesis of acne, and IGF-I levels showed a positive correlation with the severity of acne in women with clinical acne." (PMID 36551286, 2022). "Insulin-like growth factor-1 (IGF-1) has also been shown to cause excess sebum production and cause acne independently." (PMID 35677010, 2022). "High glycemic and dairy diets are likely associated with high IGF-1 levels in serum, as has been found in acne affected individuals." (PMID 35910763, 2022). "Meanwhile, high adherence to a Mediterranean diet - characterised by an omega-3 rich, low-GI diet – was associated with a protective effect against acne, possibly by anti-inflammatory and anti-IGF1 mechanisms." (PMID 33773591, 2021). "Elevated IGF-1 and insulin that is mediated by western diet increases sebaceous gland growth and sebaceous lipogenesis, which causes hyper- and dysseborrhea in acne patients." (PMID 31951642, 2020). "Inflammatory response in aggravated and augmented acne lesions further underlines the role of peroxisome proliferation-activating receptors (PPARs), along with insulin and an insulin-like growth factor (IGF-1)." (PMID 30400322, 2018).
acne (continued). "Enhanced androgen, TNF-α and IGF-1 signalling due to genetic polymorphisms promoting the risk of acne all converge in mTORC1 activation, which is further enhanced by nutrient signalling of WD." (PMID 23614736, 2013). "IGF-1 is a strong stimulator of sebaceous lipogenesis and acne pathogenesis has been linked to elevated IIS with consecutive nuclear FoxO deficiency." (PMID 21699736, 2011). "The results indicated that IGF-1 deficiency helps inhibit the occurrence of acne." (PMID 41003387, 2025). "This suggests that IGF-1 may play a role in the pathogenesis of acne vulgaris and understanding this underlying pathophysiology is important for patients to remain compliant in their medication management with GLP-1 agonists." (PMID 38586157, 2024). "Dietary habits, particularly the consumption of high-glycemic-index foods and dairy products, have been linked to acne severity, possibly due to their role in insulin-like growth factor 1 (IGF-1) signaling, which can exacerbate sebum production and inflammation." (PMID 38791344, 2024). "In contrast, lysozyme cannot kill C. acnes, which may explain its minor upregulation in acne skin biopsies.The expression of AMPs can also be affected by several AV-associated factors, such as FFAs, glucose, insulin, or IGF-1 levels." (PMID 39744637, 2024). "The association found between milk intake and acne may be due to its compounds, such as certain amino acids, being able to stimulate the synthesis of IGF-1." (PMID 37447169, 2023). "Fluctuations in insulin and IGF-1 levels can affect seborrhea, one primary cause of acne." (PMID 37892480, 2023). "On the other hand, consumption of dairy milk products has been associated with a higher frequency and severity of acne, as its components enhance the effects of insulin and IGF-1 on the production of androgen hormones and sebum and stimulate the formation of comedones." (PMID 37727660, 2023). "Similarly, with reference to IGF1, the length of CA repeats was found to be significantly associated with acne risk only, and the risk of both acne and more severe forms of acne." (PMID 33849530, 2021). "High levels of omega-3 fatty acids found in fish and the high fiber content in fruits and vegetables may reduce acne risk by decreasing the Insulin-like growth factor 1 (IGF-1) level and increasing sex hormone-binding globulin (SHBG) level." (PMID 34133464, 2021). "Notably, dietary variables such as intake of fish, fruits and vegetables were suggested to influence acne and severe acne risk by modulating IGF-1 levels, showing a possible interaction between genetic factors and modifiable risk factors." (PMID 33849530, 2021). "The relationship between IGF-1 and androgens and their effects on the sebaceous gland have brought into question whether high glycemic loads can lead to increased IGF-1 release and thus an increased risk of acne." (PMID 34207527, 2021). "Foods rich in dairy and carbohydrates increase the risk of acne, probably by elevating IGF-1." (PMID 31284694, 2019). "Therefore, AMPs could be key determinants in regulating AV development and progression, linking acne-associated immune responses and metabolic factors, like insulin/IGF-1 and PI3K/Akt/mTOR/FoxO1 signaling pathways or glucotoxicity." (PMID 39744637, 2024). "Therefore, AMPs may be key determinants in developing and progressing acne-associated immune responses, skin barrier integrity, and metabolic factors, like insulin/IGF-1 and PI3K/Akt/mTOR/FoxO1 signaling pathways or high glucose levels." (PMID 39744637, 2024). "Moreover, studies indicate that regular intake of probiotics, particularly those containing lactobacillus strains, over 12 weeks is associated with a significant reduction in inflammatory acne lesions (30% to 67%) and a concurrent decrease in IGF-1 levels by 32%." (PMID 38556870, 2024).
acne (continued). "Milk and dairy products can increase insulin and IGF-1 levels and activate the nutrient-sensitive kinase mammalian target of rapamycin complex-1 (mTORC1), which promotes anabolic pathways associated with increased seborrhea and follicular hyperkeratosis, both involved in acne development." (PMID 37892480, 2023). "For example, several studies found that frequent consumption of certain dairy products, carbohydrates, high GI and glycaemic load (GL) diet is a potential risk factor for acne, which could be attributed partly to the insulin-like growth factor 1 (IGF1)/FoxO1/mTORC1 signalling pathway." (PMID 33773591, 2021). "The omega-3 fatty acids found in fish and the high fiber content in fruits and vegetables, could explain these observed protective effects from the consumption of these Mediterranean foods, which have been reported to lower the insulin-like growth factor 1 levels, thus reducing acne risk." (PMID 33902622, 2021). "Furthermore, serum IGF-1 deficiency has been shown to prevent the occurrence of acne." (PMID 33255783, 2020). "Patients affected by acne present higher serum levels and epidermal expression of IGF-1, and subjects with the IGF-1 congenital deficit, such as in Laron syndrome, never develop the disease." (PMID 40422250, 2025). "Some target genes were likely involved in acne development, including AR, IGF1/IGF1R, mTOR, GATA6, Wnt, IL6, FOXO1, PIK3, MYC." (PMID 40625748, 2025). "Whey protein increases insulin and IGF-1 signaling, which upregulate androgenic pathways, sebaceous gland activity, and keratinocyte proliferation-major contributors to acne pathogenesis." (PMID 40688823, 2025). "Insulin-like growth factor-1 (IGF-1) signaling is one of the most critical pathways in the development of acne, which can induce the expression of pro-inflammatory cytokines (IL-1β, IL-6, IL-8, and TNF-α) and MMP in human sebum cells." (PMID 40362847, 2025). "Insulin‐like growth factor‐1 (IGF‐1) is thought to be the main driver of inflammation in acne that is responsive to Isotretinoin." (PMID 39927601, 2025). "The insulin/IGF-1 pathway over-stimulation in acne patients results in the hyper-stimulation of DNL and thus in excessive and deregulated sebum production." (PMID 40422250, 2025). "The importance of the insulin/IGF-1 pathway in acne pathogenesis is also strengthened by the higher prevalence of acne in Western countries, therefore highlighting the role of the high-glycaemic load diet in acne onset and exacerbation." (PMID 40422250, 2025). "Studies have shown that acne is an androgen-dependent sebaceous gland disease driven by insulin-like growth factor 1 (IGF-1)." (PMID 41003387, 2025). "This suggests modulation of the IGF-1 signaling axis, a pathway involved in sebocyte lipogenesis and keratinocyte proliferation, both central to acne pathophysiology." (PMID 41614884, 2025). "The IGF-1/PI3K/AKT signaling pathway promotes the development of acne, with AKT activation prompting the phosphorylation of the FoxO1 nuclear transcription factor, reducing its nuclear presence and relieving its inhibitory effect on androgen receptors." (PMID 41003387, 2025). "IGF-1 is a key player in acne pathogenesis, and the IGF-1-induced PI3K/Akt/FoxO1/mTOR C1 pathway is considered to be the most important pathway leading to acne pathogenesis." (PMID 38585341, 2024). "Although milk has a low glycemic index, it can aggravate acne by increasing insulin and insulin growth factor-1 (IGF-1) levels and releasing comedogenic hormones like estrogen, progesterone, androgen precursors, and 5α-reductase steroids." (PMID 38633058, 2024). "This is likely because the bacterium of the P. acnes phenotype, which is involved in the development of acne, is found in dairy and IGF-1, which is also found in dairy and plays a role in acne pathogenesis." (PMID 38388743, 2024).
acne (continued). "Another study suggested the existence of a link between the Mediterranean diet and lower levels of IGF-1, a pivotal molecule involved in the pathophysiology of acne." (PMID 39458553, 2024). "In nutrient-sensing acne, IGF-1 promotes the nuclear export of forkhead box O1 (FoxO1) by phosphorylating PI3K and Akt, leading to sebum overproduction and altered lipid profile." (PMID 39349732, 2024). "The blue cluster is primarily related to acne (including western diet, insulin like growth factor 1, milk consumption, quality-of-life, and anxiety)." (PMID 38788015, 2024). "In this study, we investigated the effects of Pae on acne development induced by IGF-1 in SZ95 sebocytes." (PMID 39349732, 2024). "Such diets increase insulin and insulin-like growth factor 1 (IGF-1) levels, which then stimulate sebum production and androgen hormone release, which ultimately results in the development of acne." (PMID 39624570, 2024). "A previous study has proven that the proliferation of keratinocytes was enhanced by IGF-1 via the activation of IGF-1r in the development of acne vulgaris." (PMID 38197658, 2024). "IGF-1 signaling, critical in acne development, regulates the PI3K/Akt cascade and FoxO1 activity, impacting lipogenesis and androgen receptor (AR) transactivation and influencing lipid synthesis and sebaceous secretion." (PMID 38791344, 2024). "Among these, IGF-1 is crucial in exacerbating the acne pathogenesis, contributing to the progression and severity of the disease through increased sebum secretion and heightened proliferation of keratinocytes and sebocytes." (PMID 39458553, 2024). "The mechanisms by which an anti-inflammatory diet affects acne include the regulation of insulin and IGF-1 levels, which are involved in sebum production and inflammatory processes." (PMID 38998499, 2024). "Insulin and insulin-like growth factor (IGF-1) can promote increased sebum production and the growth of keratinocytes, which leads to clogged pores and the formation of acne lesions." (PMID 38998499, 2024). "The hyperinsulinaemia induced by the insulinotropic function of such proteins also raises IGF-1 concentrations, providing a possible reason to explain why people consuming these supplements struggle with the appearance or exacerbation of acne lesions." (PMID 38794714, 2024). "The inhibition of the production of these proteins implies the increased availability of androgens and IGF-1, thus enhancing the exacerbation of acne." (PMID 38794714, 2024). "IGF-1 is another crucial hormonal driver, influencing acne by downregulating the nuclear transcription factor forkhead box protein O1 (FoxO1), which, in turn, increases lipogenesis and androgen receptor transduction." (PMID 38791344, 2024). "Analysis of skin biopsies from these participants revealed a decrease in IGF-1 levels alongside an increase in FoxO1 gene expression, suggesting a positive regulatory effect on acne-related markers." (PMID 38791344, 2024). "While studies have reported a positive correlation between plasma IGF-1 levels and the clinical severity of acne, insulin resistance has recently been reported in rosacea patients." (PMID 37892480, 2023). "The consumption of dairy foods, particularly milk, and high glycemic carbohydrates, a common dietary pattern seen in acne patients of Westernized populations, increases circulatory levels of IGF-1 and insulin." (PMID 36729355, 2023). "Insulin/IGF-1 and androgens trigger the mTOR pathway, which represents a central node between puberty, diet, and acne onset." (PMID 37727660, 2023). "According to the literature, IGF-1/PI3K/AKT signalling contributes to the development of acne lesions." (PMID 36803994, 2023). "Another study describing this issue showed that the frequency of IGF-1 genotype (CA) 19 was significantly different between control and acne patients (p = 0.0002)." (PMID 36986218, 2023).
acne (continued). "Increased serum IGF-1 levels correlate with acne lesion counts in females and increased sebum secretion rates in male acne patients." (PMID 37998335, 2023). "Due to the implication of a high glycemic diet and insulin/IGF-1 in the pathogenesis of acne, mechanisms of abatement of insulin level or action are useful targets in the treatment of this disorder." (PMID 37727660, 2023). "IGF-1 is considered as a key trigger to the development of acne, primarily due to its ability to enhance the functioning of sebaceous glands (SGs), resulting in heightened sebocyte proliferation, differentiation, and lipid synthesis." (PMID 38062074, 2023). "Elevated levels of androgens, insulin, and insulin-growth factor-1(IGF-1) lead to the promotion of hyperkeratosis and hyperseborrhea, resulting in acne formation." (PMID 37626790, 2023). "IGF-1 is overexpressed in the epidermis and pilosebaceous units of acne patients compared to controls." (PMID 37998335, 2023). "A visible indicator disease of exaggerated IGF-1 signaling is acne vulgaris, the most common inflammatory skin disease in industrialized countries, which is associated with increased height and BMI during puberty." (PMID 36729355, 2023). "To clarify the effects of emodin in acne‐mimicking lipid synthesis, we induced sebocyte differentiation and lipogenesis by stimulating with 20 ng/ml IGF-1." (PMID 38062074, 2023). "A study of 40 acne patients and 20 controls showed that the patients exhibited considerably higher serum IGF-1 levels than controls." (PMID 35163615, 2022). "Among others, IGF-1 and IGF-1R are well-known targets of C. acnes, where IGF-1 induces lipid synthesis in human sebocytes and plays an important role in the development of acne." (PMID 36551286, 2022). "After 12 weeks of treatment, changes in expression of IGF-1 and FoxO1 genes were compared in skin areas with acne lesions." (PMID 35889022, 2022). "Hyperglycemic diets can induce IGF1 production and IGF1 signaling contributes to the pathogenesis of acne." (PMID 36439142, 2022). "The PI3K/Akt/FoxO1/mTORC1 of the Mammalian Target of Rapamycin (mTOR) C1 pathway induced by IGF-1 is known to be involved in the pathogenesis of acne." (PMID 35966699, 2022). "This association is explained by the influence of refined carbohydrates on numerous factors related to acne development and progression, including insulin-like growth factor-1 (IGF-1), IGF-binding protein, and androgen level." (PMID 35807855, 2022). "Inflammation is the fingerprint of acne pathogenesis, driven by Insulin-like Growth Factor (IGF-1), altered sebum production, and C. acnes." (PMID 35910763, 2022). "The present results showed that the activities of SREBP-1 and PPAR-γ were increased in living C. acnes- and IGF-1-induced acne vulgaris models." (PMID 36551286, 2022). "This study investigated the potential pharmacological effects of BV and its major component, melittin, on models of acne induced by C. acnes in vivo and by IGF-1 in human sebaceous gland cells." (PMID 35328573, 2022). "Recent research indicates that diets with a high glycemic load promote the acne vulgaris disease by increasing the IGF-1 levels." (PMID 36678524, 2022). "The PI3K/Akt/FoxO1/mTORC1 axis of the Mammalian Target of Rapamycin (mTOR) C1 pathway, induced by IGF-1, is known to be an essential signaling pathway for the pathogenesis of acne." (PMID 35966699, 2022). "A previous study reported elevated IGF-1 levels in cases of acne, potentially indicating a possible influence of insulin and growth hormone levels." (PMID 35677010, 2022). "Insulin and IGF-1 are known to increase acne formation by increasing sebum production and conversion of testosterone to dihydrotestosterone." (PMID 36161627, 2022). "Acne is an IGF-1- and androgen-dependent disease of human sebaceous glands associated with sebaceous gland hyperplasia, increased and disturbed sebaceous lipogenesis, and enhanced proliferation of acro-infundibular keratinocytes (comedogenesis)." (PMID 33803410, 2021).